MIR888 (microRNA 888)
Synonyms: hsa-mir-888; MIRN888
Gene: MicroRNA gene on chromosome X (145,994,784 to 145,994,860, reverse strand). Ensembl gene ENSG00000216005.
Diseases named in the same sentence as MIR888 in open-access papers:
MIR888 is named in the same sentence as 3 diseases in open-access papers, as found by Europe PMC text mining. Sharing a sentence is not in itself a finding about the gene and the disease. The quoted sentences say what the papers report.
colon tumors (1 paper, 2019). "We further observed that, similar to BC, MIR888 hypomethylation also occurs in all cancer types with reported miR-888-5p overexpression, which arise from tissues other than testis, such as prostate, endometrial, breast, hepatocellular, and colon tumors." (PMID 31287003, 2019).
MIR888 also shares sentences with these, for which no sentence is quoted: bladder cancer (1 paper); cancer (1).